PADI4 (peptidyl arginine deiminase 4)
Diseases named in the same sentence as PADI4 in open-access papers (continued):
Sharing a sentence is not in itself a finding about the gene and the disease.
tumor (continued). "DC-CIK cells stimulated with lysate from PADI4-overexpressing cells suppressed tumor volume by 18.6% in the tumor-bearing mice." (PMID 30944835, 2019). "This study demonstrates that stimulation of DC-CIK cells with PADI4 significantly suppressed tumor growth in tumor-bearing mice by promoting DC maturation, CIK cell proliferation, and cytotoxicity." (PMID 30944835, 2019). "Consistently, PADI4 level in the blood increased dramatically in the patients with various malignant tumors, but considerably declined after tumor excision surgery." (PMID 29212180, 2017). "PADI4 (peptidyl deiminase isoform 4) is overexpressed in many tumor tissues and converts arginine residues to citrulline residues." (PMID 27556695, 2016). "Increasing evidence suggests that PADI4 (peptidyl deiminase isoform 4) is involved in tumor progression." (PMID 27556695, 2016). "We genotyped 59 SNPs in the PADI4 locus of various tumor samples and controls using an Illumina 384-SNP VeraCode microarray." (PMID 27556695, 2016). "We previously detected the citrullination of keratin and co-localization of PADI4 with keratin in many tumor tissues." (PMID 27556695, 2016). "Recently, overexpression of PADI4 was detected in various tumors, demonstrating an ability to promote tumorigenesis by repressing tumor suppressor genes such as OKL38." (PMID 26673819, 2016). "We previously detected increased expression of PADI4 in a variety of malignant tissues and in the blood of tumor patients." (PMID 27478411, 2016). "It is worth noting that among the genes in Set A whose expression is down-regulated abound those with tumor-inhibitory activity (e.g., Pag1, PadI4, Lats2, and Cxcl3), while among the up-regulated genes are present tumor facilitators (e.g., Rab18, Dek)." (PMID 27965576, 2016). "An analysis of the relationship between Padi4 and tumor cells has also provided some insights into this topic." (PMID 26293116, 2015). "This review highlights PADI4 expression in tumour tissues as well as the potential role of PADI4 in the pathogenesis of cancer." (PMID 20222985, 2010). "Plasma PADI4 levels in patients with malignancies were considerably diminished after tumor excision surgery, suggesting that PADI4 protein circulates in the blood from corresponding tumor tissues." (PMID 19183436, 2009). "Compared to benign and non-tumor diseases, many malignant tumor types exhibited increased PADI4 expression in tumorous cells." (PMID 19183436, 2009). "Because the cAT content in the plasma declined after tumor excision surgery and was generally associated with PADI4 levels in the blood, we propose that the high cAT levels observed in the blood was due to citrullination of PADI4 in tumor tissues." (PMID 19183436, 2009). "Due to the relatively low, sometimes undetectable, expression of PADI4 in tumor tissue extracts, we performed western blot following immunoprecipitation in the study." (PMID 19183436, 2009). "Patients with malignant tumors also displayed higher plasma levels of both PADI4 and cAT than patients with benign and non-tumor inflammations." (PMID 19183436, 2009). "To further confirm these findings, we investigated PADI4 expression by immunohistochemistry, real-time PCR and western blot analysis in various benign tumors and non-tumor inflamed tissues in the current study." (PMID 19183436, 2009). "While deletion of Padi4 has been shown to affect expression of MHC II on tumor associated macrophages, we did not measure any change in MHCII expression in monocyte-derived macrophages following GSK484 administration." (PMID 40523023, 2025). "The involvement of PADI4 in tumour progression has been substantiated by numerous studies." (PMID 40078091, 2025).
tumor (continued). "Peptidyl arginine deiminase 4 (PADI4) was recently found to be involved in HIF-dependent transcriptional response to tumor vascularization and hypoxia through histone citrullination, which might explain its correlation to poor prognosis." (PMID 38182978, 2024). "In addition, conditioned medium from the lungs of 4T1 tumor-bearing mice clearly increased Padi4 and both a NF-κB inhibitor and p65 knockdown reversed this effect." (PMID 36973439, 2023). "Next, we sought to determine whether Padi4 in tumor cells and the cognate citrullinated chromatin enhanced tumor metastasis." (PMID 36973439, 2023). "The creation of NETs leads to the secretion of several neutrophil-derived proteins and chromatin into the extracellular space within the tumor microenvironment, a process that is mediated by peptidyl arginine deiminase 4 (PADI4) and the entrance of neutrophil elastase to the nucleus." (PMID 35884400, 2022). "Increasing evidence suggests that PADI4 is involved in tumour progression." (PMID 35045833, 2022). "Moreover, it has been reported that PADI4 plays a crucial function in tumour cell proliferation, apoptosis and EMT." (PMID 35045833, 2022). "Similarly, PADI4 mRNA expression measured by real-time PCR was also significantly increased in GC tumour samples compared with paired adjacent normal gastric tissue samples (p = 0.002)." (PMID 35045833, 2022). "PADI4 also can accelerates cell activity and tumour growth in tumour-bearing tissues in vivo." (PMID 35045833, 2022). "Additionally, our real-time PCR showed that tumours in mice injected with PADI4-overexpressing MGC80-3 cells exhibited strong PADI4 expression(P = 4.4*10–8)." (PMID 35045833, 2022). "Given the importance of PADI4 in the development of tumor cells and the involvement of importins in such processes, our results can provide a molecular description of the basic binding mechanism that may lead to cancer progression." (PMID 35883608, 2022). "Last, we performed the in vivo experiment in nude mice and results also showed PADI4 could affect the tumor growth." (PMID 34055985, 2021). "PADI4 may be a potential tumor marker that could be used to improve the therapeutic efficiency of DC-CIK cells." (PMID 30944835, 2019). "Among them, is relevant PadI4, which by demethylating histones may act as a tumor suppressor; thus, its down-regulation in Set A could enhance tumorigenesis." (PMID 27965576, 2016). "Most striking were the large distances seen between PAD14, HDAC10 or DOT1L to other genes in the benign tissue dataset, with only PADI4 remaining isolated in the tumor tissue, suggestive of new tumorigenic transcriptional networks involving HDAC10 and independently, DOT1L." (PMID 27863398, 2016). "Interestingly, we found that PADI4 mRNA expression of tumor tissues was higher in MDR1 (+) group (Mean -∆Ct ± SD = 0.59 ± 0.37) than that in MDR1 (-) group (Mean -∆Ct ± SD = -1.69 ± 0.53)." (PMID 25922661, 2014). "Taken together, PADI4 could play an important role in inducing chemoresistance in HCC cells, and the expression of PADI4 of tumor tissues in HCC patients could be used as a prognostic indicator." (PMID 25922661, 2014). "Studies have demonstrated the high expression of PADI4 in various malignant tumour tissues." (PMID 20222985, 2010). "In addition, the specific nature of PADI4 expression in tumour cells makes PADI4 a potential target for cancer therapy." (PMID 20222985, 2010).
tumor (continued). "Their findings may explain the disappearance of CD34 expression in PADI4-expressing tumour cells observed in our study." (PMID 20222985, 2010). "TaqMan quantitative PCR was used to measure PADI4 transcription in tumor samples." (PMID 19183436, 2009). "However, we detected PADI4 primarily in the cytoplasm of tumor cells in most malignant tissues as well as citrullinated cytokeratin in certain malignant tumors." (PMID 19183436, 2009). "PADI4 was also expressed in several mesenchymal cells in both tumor and non-tumor inflamed tissues." (PMID 19183436, 2009). "Consequently, the mechanism by which PADI4‐mediated citrullination affects cisplatin resistance might involve modulating the IDs family and tumour stemness of OSCC through the de‐ubiquitination of PRMT2." (PMID 40078091, 2025). "Therefore, it is suggested that Fn may also be citrullinated by PADI4 in tumours, thus leading to tumour cell invasion, proliferation, and malignancies." (PMID 20222985, 2010). "Furthermore, western blot analysis detected PADI4 expression in cultured tumor cell lines." (PMID 19183436, 2009). "To further investigate the role of PADI4 in LIHC, we first analyzed its expression in tumor and adjacent normal tissues from clinical LIHC patient samples." (PMID 41208994, 2025). "The mRNA expression of tumor-related key genes in the MDA-MB-231 and MCF-7 cells treated with PADI4 antibody was examined using qRT-PCR." (PMID 37804426, 2023). "PADI4 small molecule compound inhibitors (amide and chloramine) can inhibit PADI4 enzyme activity in HL-60, MCF-7, and HT-29 tumor cells, ultimately inhibiting the activation of cancer cells." (PMID 37804426, 2023). "Studies have shown that PADI2, PADI3 and PADI4 in the PADI family promote the carcinogenic microenvironment by mediating the formation of EVs, leading to tumor invasion." (PMID 37020554, 2023). "In previous experiments, we cocultured PADI4 recombinant protein with DC-CIK cells and found that it significantly inhibited tumor growth in tumor-bearing mice by promoting DC maturation, CIK cell proliferation, and cytotoxicity." (PMID 37804426, 2023). "PADI4 upregulates the expression levels of KRT14, CXCR2 and TNF-α, which are related to cell proliferation, cell migration, tumour angiogenesis, and tumour immune microenvironment." (PMID 35045833, 2022). "We further validated the expression of PADI4 and Wnt/β-catenin and MEK/ERK signaling pathway proteins (p-ERK and active β-catenin) by means of IHC in tumor and adjacent normal tissues." (PMID 34055985, 2021). "PADI4 is expressed in CD34+ stem cells in normal tissues, and many more CD34+ cells expressing PADI4 are present in tumour tissues." (PMID 20222985, 2010). "Multiple MET markers (CitH3, MPO, MMP2, MMP9, and MMP12) were elevated in macrophages that were co-cultured with tumour cells, but this effect could be rescued by treatment with MET inhibitor (Cl-amidine, a specific PADI4 inhibitor) or GW." (PMID 39025845, 2024). "PADI4 shows different molecular weights in different studies, and even the molecular weight of PADI4 is not completely the same in the same tumor cells." (PMID 37804426, 2023). "The tumor cells were treated with PADI4 antibody, and cell proliferation, migration, colony formation, apoptosis, glycolysis, and epithelial-mesenchymal transition (EMT) were measured as well as the expression of some essential tumor genes." (PMID 37804426, 2023). "In cancer, high PADI4 expression has been connected to tumor growth, as PADI4 was overexpressed in numerous malignant cancers, but not in healthy tissues." (PMID 29212180, 2017).
tumor (continued). "PADI4 is highly expressed in a variety of malignant tumours but is either not expressed or is expressed at very low levels in normal tissues and benign tissues." (PMID 20222985, 2010). "We previously detected intense PADI4 expression in tumor cells from various adenocarcinomas, but not in healthy tissues." (PMID 19183436, 2009). "In addition, PADI4 was detected in total protein extracts from A549, SKOV3 and U937 tumor cell lines." (PMID 19183436, 2009). "In the current study, we demonstrated the presence of extensive PADI4 expression in malignant tissues, but not in most benign and non-tumor tissues." (PMID 19183436, 2009). "Furthermore, PADI4 knockdown resulted in an upregulation of E-cadherin and a downregulation of Vimentin (P<0.05), indicating that PADI4 depletion may inhibit the EMT process, further supporting its role in tumor progression and metastasis." (PMID 41208994, 2025). "Notably, when compared side by side, tumor-specific, but not myeloid-specific, Padi4 deletion substantially decreased lung metastasis." (PMID 36973439, 2023). "Moreover, RNA-seq of lung metastatic tumor cells revealed increased Padi4 messenger RNA but not in other Padi family members." (PMID 36973439, 2023). "Notably, myeloid-specific Padi4 deletion did not have any effect on metastasis or on primary tumor growth, discounting the involvement of Padi4-mediated NETosis." (PMID 36973439, 2023). "On the other hand, the degradation of extracellular DNA, including that in CECNs, by DNase Ι effectively inhibited the pulmonary metastasis of PADI4-expresing 4T1 cells without affecting circulating tumor cells and reduced metastasis following intravascular perfusion." (PMID 36365233, 2022). "Experiments both in vitro and in an animal model demonstrate that incubation with PADI4 protein can significantly promote DC maturation, CIK cell proliferation, and elevate cytotoxicity and that PADI4-stimulated DC-CIK cells significantly suppressed tumor growth in tumor-bearing mice." (PMID 30944835, 2019). "However, PADI4 rs2240337 G>A SNP did not correlate with clinical tumor stage (p = 0.215) or grade (p = 0.497)." (PMID 29212180, 2017). "Moreover, this study found that PADI4 may contribute to cancer development and progression by increasing the expression of CXCR2, KRT14 and TNF-α, which activate pro-inflammatory processes, angiogenesis, cell migration, cell proliferation and cell differentiation in tumor tissues." (PMID 27556695, 2016). "Although tumour cells that express PADI4 lacked CD34 signals, the enzyme is located in CD34+ mesenchymal cells in the stromal region of the tumour tissues." (PMID 20222985, 2010). "Expression of PADI4 was investigated in various tumors and non-tumor tissues (n = 1673) as well as in A549, SKOV3 and U937 tumor cell lines by immunohistochemistry, real-time PCR, and western blot." (PMID 19183436, 2009).
cancer (107 papers, 2009 to 2026). A tumor composed of atypical neoplastic, often pleomorphic cells that invade other tissues. "Peptidylarginine deiminase 4 (PADI4) regulates protein citrullination and is associated with various cancer developments." (PMID 40078091, 2025). "This suggests that cells that aberrantly upregulate or activate PADI4, either through genetic mutation or deregulation of PADI4-activating signalling pathways, have a growth advantage and are selected during cancer development and metastasis." (PMID 35706669, 2022). "PADI4 is known to be implicated in cancer and is thought to respond to estrogen-simulation in MCF-7 cells through both genomic and non-genomic mechanisms." (PMID 30483308, 2018). "Future work will be needed to address this exciting potential role of PADI4 deregulation in causing DNA methylation alterations in cancers." (PMID 24957603, 2014). "When a combination of DNA, PPBP and PADI4 was considered, a unit increase in log DNA, log PPBP or log PADI4 was associated with a six-, five- and two-fold increase in cancer risk, respectively." (PMID 23468981, 2013). "Thus, PADI4 deregulation is strongly associated with the pathophysiology of inflammatory disorders, autoimmunity and cancer." (PMID 37778387, 2023). "Importantly, these studies showed that loss of PADI4 in mice reduced both NETs formation and cancer metastasis." (PMID 35706669, 2022). "To gain further insight into its tumorigenic mechanism, we investigated whether common polymorphisms in the PADI4 region are associated with various cancer risks using a SNP microarray." (PMID 27556695, 2016). "Nuclear expulsion occurs in apoptotic cancer cells in a peptidylarginine deiminase 4 (Padi4) dependent manner." (PMID 40751052, 2025). "Numerous studies have posited that protein citrullination catalysed by PADI4 is a significant aspect of PADI4's role in cancer pathogenesis." (PMID 40078091, 2025). "In PADI4 knockout mice, tumor growth is slower, and deoxyribonuclease treatment reduces cancer growth by inhibiting NETs." (PMID 40443678, 2025). "Key transcripts such as H3C10, H1-2, PADI4, and others were identified as crucial in regulating the chromatin architecture and gene expression, which are essential for cancer progression and metastasis." (PMID 39000413, 2024). "There was a very high overlap between hypoxia-inducible genes regulated by HIFs and those that depended on PADI4 expression, suggesting that, at least in cancer cells, PADI4 is a global co-activator of HIFs." (PMID 36899934, 2023). "Two of the PADI4 variants and the TP53INP1 variant have been detected in other cancer types in the COSMIC database." (PMID 38259614, 2023). "PADI4 can participate in the proliferation and metastasis of cancer cells through certain signaling pathways." (PMID 37020554, 2023). "Here we report that apoptotic cancer cells enhance the metastatic outgrowth of surviving cells through Padi4-mediated nuclear expulsion." (PMID 36973439, 2023). "PADI4 has been reported to be expressed in the cytoplasm and nucleus in a variety of malignant tumors." (PMID 37804426, 2023). "Aberrant PADI4 expression and activity are features of various inflammatory diseases and cancers and PADI4 has been shown to act as a cofactor to key oncogenic transcriptional regulators." (PMID 37778387, 2023). "Together, these findings demonstrate that cancer-derived citrullinated chromatin occurs in vivo and likely enhances lung metastasis through mechanisms independent from Padi4-induced NETs." (PMID 36973439, 2023). "Our studies demonstrate that Padi4-expressing apoptotic cancer cells undergo nuclear expulsion and release a DNA/protein structure or NEPs that promotes metastatic outgrowth." (PMID 36973439, 2023). "PADI4 can participate in the proliferation and metastasis of cancer cells by regulating gene expression." (PMID 37020554, 2023).